DCLK1 (doublecortin like kinase 1)
Diseases named in the same sentence as DCLK1 in open-access papers (continued):
Sharing a sentence is not in itself a finding about the gene and the disease.
cancer (continued). "However, we should note that the literature on DCLK-1′s effect on cancers produced mixed results." (PMID 40869256, 2025). "Additionally, our findings from the TCGA-CCA cohort indicated a significant elevation in DCLK1 mRNA expression in CCA tissue (5.39 ± 1.40) compared to para-cancer tissue (3.52 ± 1.18) (t = 3.63, P < 0.001), aligning with the results observed in our IHC analysis." (PMID 38980538, 2024). "Thus, DCLK1 is a crucial therapeutic target for treating cancer." (PMID 37443105, 2023). "Furthermore, Dclk1 has been shown to play important roles in various types of cancer." (PMID 37594553, 2023). "Importantly, we demonstrated that DCLK1 inhibitor could block CCAR1/β‐catenin pathway‐mediated cancer stemness and consequently suppressed 5‐fluorouracil resistant CRC cells in vitro and in vivo." (PMID 35522902, 2022). "To further explore the underlying mechanism of DCLK1‐mediated cancer stemness and 5‐fluorouracil resistance, we identified CCAR1 as a protein interacting with DCLK1, and elucidated that the C‐terminal domain (Pro301 to Met729) of DCLK1 was indispensable for interacting with CCAR1." (PMID 35522902, 2022). "Therefore, DCLK1 plays an essential role in maintaining cancer stemness." (PMID 35522902, 2022). "Importantly, we demonstrate that DCLK1 inhibitor could block CCAR1/β‐catenin pathway‐mediated cancer stemness and consequently suppresses 5‐fluorouracil resistant CRC cells in vitro and in vivo." (PMID 35522902, 2022). "Collectively, our findings reveal that DCLK1 promotes 5‐fluorouracil resistance in CRC by CCAR1/β‐catenin pathway‐mediated cancer stemness, and suggest that targeting DCLK1 might be a promising method to eliminate cancer stem cells for overcoming 5‐fluorouracil resistance in CRC." (PMID 35522902, 2022). "In addition, the physiological significance of DCLK1 kinase activity is unknown, even though it is a target for the development of kinase inhibitors due to its prominent role in cancer." (PMID 34310279, 2021). "In 2008, the Houchen group proposed that DCLK1 is a specific marker protein for intestinal adenoma stem cells, which brought attention to DCLK1 in cancer research and was the first of a series of research reports providing evidence that it might be an effective target for oncology drug development." (PMID 33348546, 2020). "Importantly, Dclk1 can discriminates between cancer and normal stem cells in the intestine." (PMID 32296643, 2020). "Since Dclk1 as a microtubule regulator marks a morphologically distinct and functionally unique population of cancer-initiating cells with molecular features of gastrointestinal tuft cells, we co-stained the sections with antibodies for Acetylated Tubulin (AcTub) and Dclk1, respectively." (PMID 31040926, 2019). "Upregulation of DCLK1 is clinically associated with the aggressiveness and poor prognosis of several cancers, whereas targeting DCLK1 via a specific monoclonal antibody can block cancer cell invasion and metastasis, thus suggestive of a potential therapeutic target for DCLK1 in cancer metastasis." (PMID 31223610, 2019). "Similarly, the NLR of 0.46 (95% CI = 0.39–0.55) indicated that low expression of DCLK1 might help exclude non-cancer individuals." (PMID 29246000, 2017). "Therefore, we conducted the comprehensive meta-analysis on all eligible studies to clarify these and assess the clinical value of DCLK1 in cancer diagnosis and prognosis, thereby providing more evidence for clinical practice and accelerating further investigations." (PMID 29246000, 2017). "DCLK1 expression could aid in the prognostication and management of this special cancer subtype." (PMID 26621833, 2016). "DCLK1 is now suggested to be a master regulator, regulating the pluripotency factors, including Nanog, Oct4, Sox2, Klf4, and Myc, that are critical for stemness of cancer cells and EMT transcriptional factors, including Snail, Slug, Twist, and Zeb1 for metastasis and survival in many solid tumors." (PMID 27335684, 2016).
cancer (continued). "Furthermore, crocetinic acid decreased the number and size of the pancospheres in a dose-dependent manner, and suppressed the expression of the marker protein DCLK-1 (Doublecortin Calcium/Calmodulin-Dependent Kinase-1) suggesting that crocetinic acid targets cancer stem cells (CSC)." (PMID 26317547, 2015). "Thus DCLK1 may contribute to the metastatic process and targeting this kinase should be considered as part of an anti-cancer therapy." (PMID 26579493, 2015). "DCLK1 plays a key role in regulating TME and is a key factor in cancer stemness and radioresistance." (PMID 40563698, 2025). "Through its role in promoting cancer stemness and EMT properties, DCLK1 overexpression drives tumorigenesis, proliferation, metastasis, and drug resistance, leading to cancer recurrence and poor patient survival." (PMID 40775208, 2025). "However, the mechanism mediating DCLK1 activation and choice of AP model in cancer remains unclear." (PMID 40775208, 2025). "Recent research suggests that DCLK1 displays the characteristics of cancer stem cells (CSC) and was highly expressed in several cancers." (PMID 40963862, 2025). "What is identifiable is that DCLK1 modulates several pathways important in cancer progression, such as the epithelial-to-mesenchymal transition (EMT), cancer stemness, inflammation, and metastasis." (PMID 38003596, 2023). "Insights into their dynamics, such as the differential expression of CD44 and DCLK1 isoforms or the regulatory role of KDM3A, can provide potential therapeutic strategies for more effective cancer treatments." (PMID 38003596, 2023). "Moreover, given the recalcitrance of advanced CRC in general, the therapeutic approach of DCLK1 kinase inhibition may have the potential to overcome the limitation of current therapies by suppressing the cancer stemness and inflammatory TME that fuel fatal recurrence and metastasis." (PMID 35910805, 2022). "In the current study, we applied DCLK1‐IN‐1 to targeting DCLK1, and found that DCLK‐IN‐1 suppressed 5‐fluorouracil resistant CRC cells by inhibiting CCAR1/β‐catenin pathway‐mediated cancer stemness." (PMID 35522902, 2022). "DCLK1 and two are understudied kinases, with the majority of work being upon DCKL1 and its role in cancer, neuronal survival, and maintenance of intestinal crypt cell stemness." (PMID 36686695, 2022). "Another molecule that participated in the EMT process is doublecortin-like kinase 1 (DCLK1), a cancer stem cell marker." (PMID 35444536, 2022). "DCLK1 is a validated novel CSC marker in the gastrointestinal tract and there is emerging evidence for an equivalent role in other cancers, including HNSCC." (PMID 34336664, 2021). "Multiple markers have been identified that are present in normal intestinal and cancer stem cells, including, but not limited to CD44, CD24, CD166, CD133, telomerase (TERT), doublecortin calmodulin-like kinase 1 (DCLK1), and LGR5." (PMID 34206989, 2021). "Prior studies of DCLK1 show that it has a regulatory role in EMT, a key pathway driving metastatic transformation in cancer." (PMID 34830884, 2021). "Overexpression of DCLK1 was found essential for cancer progression, epithelial-mesenchymal transition (EMT), and metastasis of many types of cancer through downregulating tumor suppressor microRNAs." (PMID 34445192, 2021). "Certain kinase inhibitors have been found to inhibit DCLK1 kinase activity, such as that of LRRK2-In-1, XMD-892 and DCLK1-IN-1; however, they are in the process of preclinical trials for cancer treatment." (PMID 33762936, 2021). "Montelukast also significantly decreased amounts of cancer-stem cells, as well as macrophage infiltration and decreased expression of ALDH1A1, DCLK1 and BCL2 in the tumor tissue." (PMID 35008546, 2021). "Given that DCLK1 and LGR5 are markers of a reserve, stress-induced and active, cycling cancer stem cells, respectively, our future studies will focus on looking at the role of the pathway in differentially regulating these two stem cell populations." (PMID 34206989, 2021).
cancer (continued). "The recent development of a potent and highly specific DCLK1 inhibitor suggests that both targets can be optimally exploited for the treatment of patients with HNSCC and other cancers driven by DCLK1 and NOTCH pathway alterations." (PMID 34336664, 2021). "This is an interesting observation because DCLK1 is increasingly being recognized as a stress-dependent reserve CSC marker in colon and other cancers." (PMID 33924995, 2021). "It was suggested that DCLK1 regulates migration, invasion and cell motility via activation of EMT, an important process for cancer initiation, cancer metastasis, and secondary tumor formation." (PMID 34336664, 2021). "Mechanistically, DCLK1 regulates NOTCH, NF-kB, KRAS, and WNT molecular signaling pathways that promote cancer growth and progression as well as support EMT and stemness of cancer cells." (PMID 31979136, 2020). "Strong evidence demonstrates that DCLK1 is a regulator of EMT in gastric, colorectal, pancreatic, breast, renal, and other cancers." (PMID 33348546, 2020). "Doublecortin-like kinase 1 (DCLK1) is a marker of GI tuft cells and has been reported to play an important role in cancer initiation and development in various cancers." (PMID 31979136, 2020). "Aside from its role as a tuft cell marker in normal tissue and as a tumor stem cell marker in cancer, previous studies have demonstrated that silencing DCLK1 functionally reduces stemness, epithelial mesenchymal transition (EMT), and tumorigenesis in cancers." (PMID 33348546, 2020). "We previously demonstrated that interruption of DCLK1 signaling blocked EMT and inhibited the invasion and migration of cancer cells." (PMID 31878090, 2019). "RT-qPCR was used to quantify the expression of TROP2 mRNA as well as that of putative markers for basal/cancer stem cells (CD49f, POU5F1 (Oct4), DCLK1, ALDH1A3) or luminal stem cells (NKX3.1) in residual tumors." (PMID 27283984, 2016). "DCLK1 also regulates the NOTCH, NFKB, and WNT molecular signaling pathways that promote cancer growth and progression and support EMT and CSCs." (PMID 27335684, 2016). "Studies from us and others supported that DCLK1 expression is critical for cancer growth, EMT, metastasis, and cancer cell self-renewal." (PMID 27335684, 2016). "Small molecule DCLK1 inhibitors siDCLK1-NP and ADC have the potential to reduce cancer initiation, progression, and metastasis by regulating EMT and CSC." (PMID 27335684, 2016). "We previously showed that a tumor/cancer stem cell (CSC) marker, doublecortin-like kinase (DCLK1) positively regulates hepatitis C virus (HCV) replication, and promotes tumor growth in colon and pancreas." (PMID 25948779, 2015). "Nevertheless, in this study, inhibition of DCLK1 results in inhibition of pluripotency markers and induction of miR-200 (EMT inhibitor) and thereby drives the cancer cells towards a differentiated state with reduced invasive properties." (PMID 24040120, 2013). "Following the knockdown of DCLK1, a significant downregulation of ZEB1, ZEB2, SNAIL and SLUG was observed following increased expression of pri-miR-200a in AsPC-1 cancer cells." (PMID 24040120, 2013). "The studies presented clearly implicate DCLK1 in the regulation of miR-143/145, miR-200, EMT, pluripotency, angiogenesis, NOTCH1, and cancer stemness." (PMID 24040120, 2013). "Given that both hypoxia and PLOD2 play critical roles in α-promoter-preferred DCLK1 activation, and that PLOD2 is a known a hypoxia-responsive gene in multiple cancers, we hypothesized that PLOD2 mediates hypoxia-induced activation of DCLK1-L." (PMID 40775208, 2025). "In addition, they found that DCLK1 positively regulates β-catenin signaling through CCAR1, which is responsible for the maintenance of cancer stem cells." (PMID 40978202, 2025).
cancer (continued). "DCLK1 isoforms 2 and 4 additionally possess a unique extracellular, non-kinase C-terminal binding region (NKEBD) that is targeted by therapeutic agents such as the monoclonal antibody CBT-15 to disrupt tumor–stromal interactions in cancer." (PMID 40563698, 2025). "In these cells, as well as in duodenal tuft cells, NLGN2 was coexpressed with doublecortin-like kinase 1 (DCLK1) (Fig. EV2C), an interactor of NLGN2 and a stemness marker in several cancers, including pancreatic preinvasive lesions, and in the gastrointestinal tract." (PMID 38413734, 2024). "Many studies have shown that the overexpression of DCLK1 in cancer cells results in induction of EMT, stemness and increased cell migration and invasion, which can be reversed with small molecules targeting the kinase domain of DCLK1." (PMID 36979969, 2023). "In addition, targeting DCLK1 with anti-DCLK1 monoclonal antibody (CBT-15) or siRNAs showed promising results in reducing tumor burden, cancer stemness, invasion, and metastasis." (PMID 36979969, 2023). "Doublecortin-like kinase 1 (DCLK1) has been reported to enhance cell regeneration and proliferation and is highly expressed in cancer, progenitor cells, and type 2 macrophages." (PMID 37996782, 2023). "Interestingly, treatments targeting the C-terminal domain of DCLK1.2 and DCLK1.4 show significant effects on cancer progression, suggesting that the C-terminal domain is important." (PMID 38003596, 2023). "The analysis of the DCLK1+ single cell staining shows they are not cancer specific but are more abundant in non-malignant tissues." (PMID 37386128, 2023). "DCLK1+ single-cell staining is present in adjacent non-malignant and cancer tissues, in cells that do not have expression of active SFKs, supporting the conclusion that these DCLK1+ single cells do not have a tuft cell phenotype." (PMID 37386128, 2023). "Herein, we highlighted a mechanism linking a CSCs maker DCLK1 and 5‐fluorouracil resistance, and demonstrated that DCLK1 inhibitor suppressed 5‐fluorouracil resistant CRC cells through inhibiting CCAR1/β‐catenin pathway‐mediated cancer stemness." (PMID 35522902, 2022). "Targeting DCLK1 using small molecules, natural, synthetic inhibitors, and technologies such as the use of mAbs, CRISPR/Cas9, and by silencing siRNA and shRNA has shown promising results in reducing cancer relapse of the tumor." (PMID 36250024, 2022). "Moreover, growing evidences demonstrated critical functions of DCLK1 in tumour initiation, progression, epithelial‐mesenchymal transition (EMT) and cancer stemness." (PMID 35522902, 2022). "Indeed, we observed that DCLK1 promoted cancer stemness in CRC, and β‐catenin inhibitor suppressed DCLK1‐mediated cancer stemness." (PMID 35522902, 2022). "DCLK1’s role in initiation of tumor growth, development metastasis, epithelial—mesenchymal transition (EMT), cancer stemness, and pro-survival signaling has been demonstrated by experiments both in vivo and in vitro." (PMID 36250024, 2022). "In summary, we have summarized the role of tuft cells in tumors and indicated the potential possibilities of tuft cells as a novel target for tumor treatment, and strategies targeting specific molecules including DCLK1 and POU2F3 can become good choices for cancers with tuft cell signatures." (PMID 36569325, 2022). "Considering that our results had proved that DCLK1 promoted cancer stemness, and DCLK1 positively regulated β‐catenin signalling via CCAR1, we speculated that DCLK1 maintained cancer stemness through β‐catenin signalling." (PMID 35522902, 2022). "These macrophage-derived cancer stem cells express stem-like markers (e.g., leucine-rich repeat-containing G-protein 5 [LGR5], doublecortin-like kinase 1 [DCLK1], epithelial cell adhesion molecule [EpCAM], CD44, and CD133) and markers for dedifferentiation and pluripotency." (PMID 35681791, 2022).
cancer (continued). "Regardless of targeting DCLK1 successfully, the identification of chemo-resistant cancer cells indicates that these technologies are non-specific and need further understanding." (PMID 36250024, 2022). "Moreover, we find that DCLK1 positively regulates β‐catenin signalling via CCAR1, which is responsible for maintaining cancer stemness." (PMID 35522902, 2022). "Due to the emerging body of evidence implicating DCLK1 in tumorigenesis, the protein appears to be a promising target for not just one, but for several types of cancers." (PMID 34310279, 2021). "However, our findings also highlight the need to clearly define the independent contributions of DCLK1 MAP function and kinase function in DCLK1-L isoforms in driving cancer and their interconnectivity to evaluate the broader utility of DCLK1-IN-1." (PMID 34545159, 2021). "Previous studies show that DCLK1 is overexpressed in gastric, pancreatic, colon, renal, and other cancers, and plays a functional role in tumor initiation, growth, metastasis, epithelial-mesenchymal transition (EMT), and cancer stemness." (PMID 31979136, 2020). "When we compared the expression levels of GLI1 and DCLK1 or LGR5 between matched pairs of normal and cancer tissues from CRC patients, we found that their expression levels were negatively correlated with MUCIN-2 expression in cancer tissue." (PMID 32814764, 2020). "In addition, DCLK1 overexpression induced the ERK MAPK pathway, which resultantly enhanced the expression of MT1-MMP that is also involved in cancer metastasis." (PMID 31223610, 2019). "Likewise, in a recent study including a murine model, colonic epithelial cells were transformed to express Ly6A/E, a stem cell marker implicating mesenchymal features, and Doublecortin-like kinase 1 (DCKL1), a marker of cancer, by the presence of E. faecalis." (PMID 31684193, 2019). "Markers of normal and CSC are shared and this represents a drawback in development of cancer drugs directed against stem cells: as opposite, doublecortin like kinase 1 (Dclk1) is a specific CSC marker and does not mark normal stem cells." (PMID 35582268, 2019). "The PLR of 5.9 (95% CI = 3.3–10.5) suggested that patients with cancer have a 5.9-fold higher chance of being DCLK1 test positive compared to individuals without cancer." (PMID 29246000, 2017). "Our results indicated that the expression of DCLK1 in cancer tissues was significantly higher than that in normal or adjacent non-tumor tissues." (PMID 29246000, 2017). "We will highlight the functional activity of DCLK1 in supporting EMT and cancer cell self-renewal, which will lead us to a better understanding of DCLK1 expression in cancer development and progression, and help us to develop targeted therapies for effective cancer treatment." (PMID 27335684, 2016). "When segregating the cases into luminal and non-luminal cancers, DCLK1 expression was associated with better DFS significantly in luminal cancers (log-rank=5.883, p = 0.015) but not in non-luminal cancers (log-rank=0.389, p = 0.533)." (PMID 26621833, 2016). "Furthermore, this review will discuss the signaling mechanism linking EMT and CSCs, and discuss how the critical regulator Doublecortin-like kinase 1 (DCLK1) supports the EMT process and stemness for cancer development and progression." (PMID 27335684, 2016). "In addition, TROP2high PC3 cells showed high mRNA levels of cancer stem cell markers such as OCT4, ALDH1A3 and DCLK1." (PMID 27283984, 2016). "Researchers suggest that DCLK1 may suppress EMT, metastasis, and CSCs in early and even advanced stage cancer." (PMID 27335684, 2016). "Analysis of the prognostic impact of DCLK1 in the IBC-NED cases and non-NED luminal cases found that DCLK1 expression was associated with better DFS (log-rank= 12.187, p < 0.001) and OS (log-rank=7.222, p = 0.007) in IBC-NED but not in non-NED luminal cancers." (PMID 26621833, 2016).